KRAS (KRas proto-oncogene, GTPase)
Diseases named in the same sentence as KRAS in open-access papers (continued):
Sharing a sentence is not in itself a finding about the gene and the disease.
tumor (continued). "Oncoproteins, such as mutant KRAS and MYC, and hypoxic states can increase cellular ROS levels that enhance tumor growth." (PMID 32108165, 2020). "Furthermore, some hotspot allele frequencies within these driver genes were relatively low, including BRAF-V600E (0.10–0.30%) and KRAS-G12V (0.11–1.26%), which could be explained by examining samples at different tumor stages and of different histological types collectively." (PMID 32180799, 2020). "In the tumor cells, activation of oncogenes, such as MYC and KRAS, and deregulation of signaling pathways, including the PI3K pathway, results in increased glycolysis." (PMID 33198082, 2020). "Downstream interruption of KRAS-NF-κB signaling (i.e., inhibition of TBK1 with TBK1 shRNA) largely overcame integrin β3-mediated stemness (i.e., less tumor sphere formation in FGβ3 cells with TBK1 knockdown)." (PMID 32514015, 2020). "In contrast, all KRAS* mice that lived 60 days after IRE + anti-PD1 treatment rejected the subcutaneous tumor challenge and were tumor-free throughout the duration of the study." (PMID 30796212, 2019). "Amplification of KRAS, PIK3CA, SMARCB and PDFGRA was detected in 1 poorly differentiated carcinoma and in 3 INT-type tumours, respectively." (PMID 30837681, 2019). "PDE6D localization patterns in human HCC tissues revealed that a cytoplasmatic PDE6D expression pattern was associated with enhanced membrane localization of KRAS (which resembles KRAS-activation), enhanced ERK-activation and advanced tumor stages." (PMID 30901922, 2019). "A miRNA dependent role for Ago2 has been established in tumorigenesis and its miRNA-independent roles have been linked to cancer initiation/progression through interactions with known tumour promoting factors (FAK, SWI/SNF, KRAS)." (PMID 31324173, 2019). "The mutations often occur in the KRAS G12 and G13 residues, which impairs the KRAS GTPase activity and renders the mutants persistently in the GTP-bound active form, thereby promoting tumorigenesis and tumor malignancy." (PMID 31803176, 2019). "This is in stark contrast to the reported frequencies in the COSMIC database, where KRAS G12D and G12V, HRAS G12D, and BRAF V600E are reported to occur in 8/2585 (0.31%), 4/2585 (0.16%), 0/2159 (0%), and 0/1844 (0%) of IDC tumor samples." (PMID 30813596, 2019). "Q61L was one of the hotspots in the KRAS gene and has been confirmed to influence response to EGFR antagonists for tumor patients." (PMID 30755180, 2019).
tumor (continued). "Gains of oncogenes including EGFR (7p12), ERBB2 (17q12), KRAS in the EGFR pathway were characteristic for LUAD and contribute to cell proliferation and tumor development, suggesting this is a core requirement for LUAD pathogenesis." (PMID 31448219, 2019). "TEAD deregulation affects well-established cancer genes such as KRAS, BRAF, LKB1, NF2, and MYC, and its transcriptional output plays an important role in tumor progression, metastasis, cancer metabolism, immunity, and drug resistance." (PMID 31212916, 2019). "Overexpression of the mutant KRAS G12V gene in wildtype KRAS tumor cells led to Treg induction through the activation of the MEK-ERK-AP1 pathway, while KRAS inhibition reduced Treg infiltration in KRAS-driven lung tumorigenesis even before tumor formation." (PMID 31775797, 2019). "Reduced expression of NRP1 in KRAS-transformed cells results in reduced SMAD2 phosphorylation and increased tumor growth." (PMID 30717262, 2019). "For example, in genetically engineered mouse models (GEMMs) of PDAC harboring mutant KRAS, EMT was found to be an early event after tumor formation." (PMID 31681587, 2019). "Accordingly, upregulation of CXCR2 has been also reported in PDAC KRAS-driven models, as well as the efficacy of blocking CXCR2 to restrain tumor growth." (PMID 31847096, 2019). "Moreover, in Kirsten rat sarcoma (KRAS)-mutated cancer upregulated TRAIL-R2 and endogenous TRAIL act in a tumour-supportive manner, a concept which does not seem to be limited to KRAS-mutated cancers and also engages tumour-favourable polarisation of immune cells." (PMID 30935038, 2019). "Overall and regardless of the type of biological sample used, the presence of a KRAS mutation has a negative influence on the prognosis of PDAC patients whether or not they undergo surgery (with complete tumour resection or whether they have locally advanced and/or metastatic PDAC)." (PMID 31248203, 2019). "GO/KEGG analysis evidenced a significant enrichment of terms related to Th17 lymphocytes and in the KRAS-mutants enriched cluster the upregulation of IL6 and MMP12 has been detected, confirming the crosstalk between tumor and Th17 cells." (PMID 31405063, 2019). "Molecular characteristics of the tumor that also affect patient survival, such as MSI, BRAF and KRAS, have only recently been included in the 8th edition of the UICC recommendations as additional indicators for clinical practice guidance." (PMID 31296182, 2019). "In particular, KRAS and NRAS mutant tumours treated with MEK inhibitor are strongly but transiently responsive to the inhibitor and more susceptible to MAPK pathway reactivation." (PMID 31126017, 2019). "In zebrafish larvae model of glioblastoma initiation, neutrophils are actively recruited to KRAS-transformed cells very early in oncogenesis via the CXCL8-CXCR1 signaling axis, and this recruitment contributes to the proliferation of tumor-initiating cells." (PMID 31474975, 2019). "Collectively, miR‐487b is regulated by DNA methylation and it functions as a tumor suppressor in CRC mainly through targeting MYC, SUZ12, and KRAS." (PMID 30791232, 2019). "All tumors were analyzed using an NGS multi-gene panel that expands the tumor genetic portrait, including genes such as BRAF, ERBB2, KRAS, and MET in addition to EGFR and ALK/ROS1, in accordance with recently updated recommendations." (PMID 30669267, 2019).
tumor (continued). "Eventually, other tumour suppressors are lost or oncogenes amplified (e.g., PTEN and KRAS, respectively), resulting in a serous tubal intraepithelial carcinoma which subsequently metastasizes to the ovary and peritoneum." (PMID 31569439, 2019). "miR-217 is also known to bind to the KRAS 3′UTR and impair its expression, leading to tumor suppressor activities in various cancers like acute myeloid leukemia, colorectal cancer and PDAC." (PMID 31523393, 2019). "TEAD2 was shown to act cooperatively with the E2F transcription factor to promote a cell-cycle gene expression program, which enabled the bypass of oncogenic KRAS addiction in PDAC and evoked KRAS-independent tumor relapse." (PMID 31212916, 2019). "KRAS also supports metastatic dissemination through repression of Raf Kinase Inhibitory Protein (RKIP), a putative tumor suppressor with roles in cell migration, motility, and epithelial-to-mesenchymal transition." (PMID 31681559, 2019). "Restoration of miR-873 in PDAC and TNBC cells directly and significantly suppresses KRAS and its downstream ERK-MAPK- and PI3K-signaling pathways, which is one of the major drivers of PDAC and TNBC cell proliferation, invasion, and tumor growth." (PMID 30654191, 2019). "Global gene expression analysis reveals that secreting factors contribute to the development of oncogenic KRAS-induced tumors and highlights a crucial role for the CXCR2 pathway in driving tumor formation." (PMID 31041783, 2019). "EREG and AREG levels have been shown to predict tumor response and disease control in patients treated with EGFR-antibodies in both, RAS or KRAS exon 2 wild-type populations." (PMID 30467535, 2018). "Intriguingly, some of these molecules are related to oncogenesis and tumour progression/metastasis, namely, HRAS, KRAS, TGFBR1, TGFBR2, RB1, ITGA6, ITGB4, mTOR, TSC2 and APLP2." (PMID 30258067, 2018). "Our approach allowed us to develop a series of compounds that bind to KRAS with high affinity, interfere with RAS PPI and inhibit RAS-dependent signalling in human tumour cells." (PMID 30093669, 2018). "In order to ascertain the anti-tumor property of miR-422a is mediated by inhibition of BCL2L2 and KRAS, four siRNA specific for BCL2L2 (si-39, si-72, si-75, si-98) and KRAS (si-52, si-92, si-118, si-177) were generated using siRNA Selection software." (PMID 29358307, 2018). "Thus, DHA might represent an attractive anti-tumor agent directed against KRAS-mutant CCSCs." (PMID 29619114, 2018). "KRAS G12D is a well-studied oncogenic driver, whereas the co-occurrence of R361C and R361H in SMAD4 indicated biallelic inactivation of this tumor suppressor [15−18]." (PMID 30220971, 2018). "Compared with triple-negative (ie, MSI-negative, KRAS and BRAF wild-type) cancers, MSI-negative tumours with KRAS (HR 1·35 [95% CI 1·11–1·64]; p=0·003) or BRAF (2·02 [1·47–2·76]; 1·20 × 10−5) mutations were associated with worse prognosis." (PMID 30042065, 2018). "Studying the combination of changes in signaling and metabolic networks that occur in cells as a result of the KRAS and BRAF oncogenes should provide insights into both fundamental tumor processes and the mechanisms by which they circumvent therapies." (PMID 29907857, 2018). "Like other cases of secondary HS, a clonal relationship between the primary PCM and secondary tumor in current case was confirmed by FISH and NGS analyses showing IGH-MAF gene rearrangement, and similar genomic alterations in KRAS, BRAF and MAK3K6." (PMID 29463311, 2018). "Moreover, we investigated the KRAS/BRAF/GNAS/PIK3CA mutational status (mutational analysis for exon 2 of KRAS, exon 15 of BRAF, exons 9 and 20 of PIK3CA, and exons 8 and 9 of GNAS) of the original tumor (pancreatic head) and the recently resected tumors from the pancreatic body and tail." (PMID 30116990, 2018).
tumor (continued). "Also, since different methods with different limits of detection (LOD) were used in KRAS clinical routine mutational analyzes, we assume that lower tumor mutational frequencies than the LOD could have been not detected." (PMID 29707145, 2018). "Here, the authors show that KRAS-mutant tumor cells require IKKα, activated via host-provided IL-1β, to promote MPE development and that co-inhibition of both KRAS and IKKα ameliorates the development of MPE in mouse models." (PMID 29445180, 2018). "IKKα is further shown to critically mediate IL-1β signaling in KRAS-mutant tumor cells, culminating in marked MPE-promoting effects delivered by C-X-C chemokine motif ligand 1 (CXCL1), and in oncogenic addiction with mutant KRAS evident as drug resistance." (PMID 29445180, 2018). "For example, MET is a proto-oncogene, KRAS is a proto-oncogene, and overexpression of RHOA leads to tumor formation." (PMID 29293623, 2018). "KRAS, NRAS and BRAF are kinases involved in the RAS-RAF-MAPK signaling pathway and also potential tumor-driven genes." (PMID 30416987, 2018). "Anti-tumor cellular immune responses may be directed against: (i) non-mutant but overexpressed targets i.e. mesothelin, NY-ESO-1, survivin, (ii) private mutated proteins (neoantigens) as well as (iii) mutant targets that are shared among different individuals (shared neoantigen), such as KRAS." (PMID 30283732, 2018). "Our findings are consistent with a pro-survival role for GSK3 in mutant KRas-dependent tumors, where GSK3 inhibition leads to c-Myc- and β-catenin-dependent tumor suppression." (PMID 30514931, 2018). "Our results demonstrate that BET inhibition displays significant therapeutic impact in genetic mouse models of KRAS-driven PDAC and NSCLC, reducing both tumor area and tumor grade." (PMID 29721157, 2018). "In multivariable analysis including age, sex, tumor histology, tumor stage, performance status, EGFR and KRAS status, EGFR wild-type (sub-distribution hazard ratio 1.81, 95% confidence interval 1.07–3.07) were associated with the increased risk of VTE." (PMID 29743116, 2018). "Overall, this work describes a mechanism by which KRAS mediates tumor survival and metabolic reprogramming in human PDAC and highlights potential therapeutic targets in the nucleotide biosynthesis pathway to overcome KRAS/MEK inhibitor resistance." (PMID 30470748, 2018). "For instance, genes such as KRAS, PTEN and APC are well-known tumor drivers in several types of cancer." (PMID 29621323, 2018). "miRNA targeting of the KRAS 3′UTR in a recent study induced cell apoptosis in vitro and exerted a tumour suppressive effect in vivo in xenograft mice models of colorectal cancer." (PMID 29703916, 2018). "To assess changes in KRAS activity, we first performed a RAS activation assay using control and tumor tissues." (PMID 30135483, 2018). "Wildtype for KRAS and a strong EGFR expression were detected in >90% of the tumor cells, thus addition of the EGFR monoclonal antibody cetuximab or panitumumab to a platinum-based chemotherapy was recommended." (PMID 30410678, 2018). "CftDNA may also be useful in evaluating tumour burden and predicting response to standard chemotherapy in early-stage CRC, with evidence indicating an association between cftDNA changes and progression-free survival and between KRAS concentration and overall survival." (PMID 30430428, 2018). "Kaplan Meier median OS estimates of patients with relapsed disease are shown, based on tumor sidedness and receipt of bevacizumab and EGFRI therapy in KRAS wild type (wt) tumors." (PMID 30623090, 2018). "The results were extrapolated into an in vivo mouse model with implanted mutant KRAS and BRAF cancer cells in which tumor growth was slowed when the animals were administered high doses of vitamin C by daily intraperitoneal injection of 4 g/kg." (PMID 30018566, 2018).
tumor (continued). "The amplification of PIK3CA, PTEN, KRAS, SOX2, DVL3, and TP63 were present in all tumor samples in M7 and M9, including N4 in M7." (PMID 29050228, 2017). "From 3 eligible studies, 138 patients with KRAS mutant NSCLC and 371 with KRAS wild-type tumor were included in the meta-analysis." (PMID 28525386, 2017). "After the diagnosis and count of tumor cells performed by cytopathologists, liquid-based cytology specimens with sufficient tumor cells were used for EGFR and KRAS testing using real-time PCR." (PMID 29290981, 2017). "The alternative pathway is that the co‐initiating clone(s) acquire additional genetic or epigenetic damage and progress to become the predominant tumor clone(s), generating carcinomas with PIK3CA or KRAS mutant subpopulations." (PMID 28755461, 2017). "Together these data demonstrate that purely ADC lesions derived from transplanted KRAS+ cells can transition to SCC, and that tumours can acquire the SCC TPC expression profile of Sca1+/NGFR+ upon Lkb1 deletion." (PMID 28387316, 2017). "As we already suggested earlier, a subset of patients (showing gene mutations in PIK3CA, HRAS, KRAS, NRAS and BRAF or ALK translocation) could benefit from a systemic treatment with a PI3K, MEK, BRAF or ALK inhibitor in the case of unresectable or metastasized tumor stage." (PMID 29312620, 2017). "In patient 5, there is one area within the tumour and normal tissue proximal to the tumour that is both exclusively CIMP-L and KRAS-wt." (PMID 28097409, 2017). "In this model, DOX treatment led to oncogenic KRAS expression in the pancreas to initiate tumorigenesis, while DOX withdrawal halted transgene expression and induced tumor regression." (PMID 29061961, 2017). "GDC-0623 has broad potency in cell-based assays, particularly in both KRAS and BRAF mutant cancer cell lines, with corresponding efficacy in xenograft tumor models." (PMID 28954413, 2017). "However, the yield of cell-free DNA may be useful in this regard: in the ctcDNA-based NGS assay, one of the four patients with tumor tissue KRAS mutations not present in the plasma had a low yield of cfDNA, suggestive of technological limitations." (PMID 29137355, 2017). "In the patients with both blood-based and tumor tissue NGS, nine (39%) were concordant for KRAS status (6 mutants and 3 wild-type)." (PMID 29137355, 2017). "Some studies indicated that cytological specimens were suitable for EGFR and KRAS testing in patients with NSCLC using different specimens, such as cell block, liquid-based cytology (LBC) or conventional smears and fresh tumor cells." (PMID 29290981, 2017). "We conclude that STK38L and KRAS gene copy number, mRNA, and protein levels are tightly correlated in human PDAC and tumor-derived cell lines." (PMID 29108249, 2017). "KRAS and BCL2 oncogenes were highly expressed in tumor tissues, whereas the tumor suppressor PTEN gene was significantly downregulated." (PMID 29268752, 2017). "In these mice, low-level MYC expression alone is insufficient to drive tumor formation, however, deregulated MYC expression accelerated mutant KRAS-induced lesion formation." (PMID 29170413, 2017). "True predictive markers such as KRAS and pre-treatment MAA-tumor-to-normal uptake ratio are excellent examples capable of informing Y-90 treatment outcomes." (PMID 28415671, 2017).